HPSE (heparanase)
Diseases named in the same sentence as HPSE in open-access papers (continued):
Sharing a sentence is not in itself a finding about the gene and the disease.
rheumatoid arthritis (6 papers, 2011 to 2025). A chronic, systemic autoimmune disorder characterized by inflammation in the synovial membranes and articular surfaces. "Elevated HPSE expression is also observed in immune cells, such as activated natural killer (NK) cells, facilitating the development of several inflammatory diseases such as rheumatoid arthritis, inflammatory lung disease, and chronic colitis." (PMID 36291066, 2022). "Heparanase activity was also found to be dramatically elevated in synovial fluid from rheumatoid arthritis (RA) patients, suggesting an important role for heparanase in promoting joint destruction and indicating heparanase as an attractive target for the treatment of RA." (PMID 23908791, 2011). "The enzyme is expressed at a low level in normal organs; however, elevated expression of heparanase has been detected in several inflammatory conditions, e.g. in the synovial joints of rheumatoid arthritis (RA) patients." (PMID 28401953, 2017).
brain tumors (5 papers, 2020 to 2024). "Treatment with the heparanase inhibitor PG545 resulted in the selective killing of pediatric brain tumor cells and reduced migratory abilities and in vivo tumor growth." (PMID 36291792, 2022). "Spyrou studied the inhibition of heparanase in brain tumor cells of children and subsequently reduced their invasive capacity, proliferation, and tumor growth in vivo." (PMID 32850434, 2020). "In contrast, metastatic brain tumors degrade the extracellular matrix with heparanase and matrix metalloproteinases, thereby growing into the brain parenchyma in an expansive and noninfiltrating pattern, resulting in higher isotropy at DWI." (PMID 33228564, 2020). "Furthermore, it has been shown that pediatric brain tumors contain higher levels of heparanase compared to healthy brain tissue." (PMID 36291792, 2022). "Expression of HPSE is also up-regulated in human pediatric central nervous system CNS embryonal cancers and medulloblastomas compared with healthy brain tissue, and treatment of pediatric brain tumor cells with HPSE inhibitors attenuates their growth." (PMID 32075104, 2020). "The results suggest that heparanase affects both tumor cells and their ECM in cases of malignant brain tumors." (PMID 32850434, 2020).
liver fibrosis (5 papers, 2013 to 2022). "To investigate the significance and involvement of heparanase in liver fibrosis, we compared the susceptibility of wild-type (WT) and heparanase-overexpressing transgenic (Hpa-tg) mice to carbon tetrachloride (CCL4)-induced fibrosis." (PMID 35805119, 2022). "The present study is aimed at elucidating the impact of heparanase on the pathogenesis of liver fibrosis, using the well-established CCL4-induced mouse model." (PMID 35805119, 2022). "The effect of Heparanase inhibition on liver fibrosis was assessed by using Picrosirius red and Masson Trichrome stainings and measuring the pro-fibrotic cytokines FGF-2 and protein kinase B (AkT) in liver homogenates." (PMID 35329997, 2022). "The expression of heparanase in liver fibrosis was investigated only in one study, which showed increased expression of the heparanase gene in the zebrafish model of HCV-related liver fibrosis." (PMID 35329997, 2022). "In the current study, to shed light on HPSE involvement in liver fibrosis, the tempo-spatial pattern of HPSE expression in the well-established animal model of CCl4-induced fibrosis was investigated." (PMID 29097791, 2017). "To further investigate the role of HPSE in the development of liver fibrosis, we studied and correlated HPSE activity measured in the plasma of patients with chronic liver disease and the stage of the disease itself, assessed by transient elastography." (PMID 29097791, 2017). "Considering the transient HPSE expression observed in the CCl4 mouse model of liver fibrosis, in the ex vivo part of this work HPSE activity was measured in the plasma of healthy subjects and patients with chronic liver disease at various stages of fibrosis, of viral or autoimmune etiology." (PMID 29097791, 2017). "Finally, HPSE activity increased in the plasma of patients with liver fibrosis but it inversely correlated with liver stiffness." (PMID 29097791, 2017). "HPSE seems to play a key role in the macrophage-mediated activation of hepatic stellate cells (HSCs), thus suggesting that HPSE targeting could be a new therapeutic option in the treatment of liver fibrosis." (PMID 29097791, 2017). "Considering that several HPSE inhibitors are currently undergoing clinical trials and have demonstrated anti-tumor efficacy and few side effects, the results of this study strongly encourage a possible future use of these drugs in the treatment of liver fibrosis as well." (PMID 29097791, 2017). "In our study, PG545 significantly reduced the level of TNF-α, and both heparanase inhibitors decreased Casp3 and LC3 levels, effects that are expected to suppress the inflammatory and the pro-fibrotic responses and result in decreased ECM deposition, leading to prevention of liver fibrosis." (PMID 35329997, 2022). "The decreased levels of AKT obtained in our study may contribute to the favorable effect of heparanase inhibition towards preventing liver fibrosis, as lower AKT levels result in reduced expression of the inflammatory cytokines, which upon prolonged activation may induce advanced liver fibrosis." (PMID 35329997, 2022).
Nephropathy (5 papers, 2015 to 2025). A nonspecific term referring to disease or damage of the kidneys. "We have recently reported, nonetheless, that heparanase overexpression preserved glomerular structure and kidney function in an experimental model of Adriamycin-induced nephropathy." (PMID 36293542, 2022). "Previous work has demonstrated an impact of the enzyme heparanase, which cleaves heparan sulfate, on diabetic autoimmunity and complications such as nephropathy." (PMID 35435227, 2022). "Since proteinuria is a major hallmark of various GDs, our findings suggest, for the first time, a nephro-protective role of heparanase during nephropathy progression in proteinuric diseases of various etiologies." (PMID 25786136, 2015).
oral cancer (5 papers, 2014 to 2025). "In this study we have explored the potential of previously selected aptamers against heparanase as promising diagnostic and therapeutic agents against oral cancer." (PMID 25295847, 2014). "In this work, we demonstrated that these anti-heparanase aptamers are capable of inhibiting tissue invasion of tumour cells associated with oral cancer and verified that such inhibition is due to inhibition of the enzyme and not due to other potentially cytotoxic effects of the aptamers." (PMID 25295847, 2014). "Causal involvement of heparanase in oral cancer is particularly well-documented 23–27." (PMID 24286246, 2014). "Nevertheless, it is very reasonable that an outstanding correlation endures between heparanase expression and activity and the metastatic potential of oral cancer cells." (PMID 36340029, 2022). "Our results of immunohistochemical staining for heparanase showed marked positivity in oral cancer cells, particularly in the cytoplasmic compartment." (PMID 36340029, 2022). "Heparanase up-regulation correlates with the invasiveness of oral cancer cell lines 23,26,27 and with oral tumour aggressiveness 24,26–28, resembling clinical/biological characteristics of HPV-positive tumours 1,3." (PMID 24286246, 2014). "Elevated levels of heparanase were also detected in the saliva of oral cancer patients." (PMID 24286246, 2014).
oral squamous cell carcinoma (5 papers, 2010 to 2025). "The aim of the present study was to investigate the expression of glucose-related protein 78 (GRP78) and heparanase (HPA) in oral squamous cell carcinoma (OSCC) and their relationship with clinicopathological parameters and potential implications for survival." (PMID 24766948, 2014).
psoriasis (5 papers, 2015 to 2025). An autoimmune condition characterized by red, well-delineated plaques with silvery scales that are usually on the extensor surfaces and scalp. "Additionally, heparanase has been described to induce the development of psoriasis form of skin inflammation in mice." (PMID 34715781, 2021). "Taken together, the significant changes in the expression of HPSE, HPSE2, SYND1 in the skin affected by psoriasis confirm alterations of ECM in such disease." (PMID 34715781, 2021). "The significant increase in the expression of heparanase-1 (HPSE), heparanase-2 (HPSE2), syndecan-1 (SYND1), metalloproteinase-9 (MMP9), and tissue inhibitor of metalloproteinase 2 (TIMP2) in biopsies of skin affected by psoriasis showed extracellular matrix alterations in psoriasis." (PMID 34715781, 2021). "Although there are no reports in the literature that correlates psoriasis with HPSE2, it is known that HPSE2 shows no catalytic activity over heparan sulfate but presents a high affinity for heparin and heparan sulfate, which can modulate the activity of the enzyme HPSE." (PMID 34715781, 2021).
acute GVHD (4 papers, 2010 to 2023). "The frequencies of the LR genotype, previously shown to be associated with a low level of HPSE expression and a low risk of developing acute GVHD, were significantly higher in the group with total and paraskeletal disease compared with control patients." (PMID 36980254, 2023). "In our previous published studies, we found that the effect of a discrepancy between recipient and donor in HPSE gene SNPs leads to an increased risk of developing acute GVHD." (PMID 36980254, 2023). "We aimed at assessing the CMV seropositivity component in heparanase SNP-associated risk for acute GVHD after HSCT." (PMID 34943994, 2021). "We show that the previously found correlation of HPSE SNPs and the risk of acute GVHD was limited mainly to CMV-seropositive recipients." (PMID 34943994, 2021). "Correlation analysis between functional HPSE SNPs and the risk of developing acute GVHD after HSCT revealed a significant association only in CMV-seropositive patients, as opposed to CMV-seronegative patients." (PMID 34943994, 2021). "The C alleles of insulator SNPs rs4364254 and rs4426765 modify the activity of the HPSE gene enhancer resulting in both altered heparanase expression and increased risk of developing acute GVHD." (PMID 34943994, 2021). "The enhancer rs4693608 SNP has a major impact on HPSE gene expression and the risk of acute graft-versus-host disease (GVHD) after hematopoietic stem cell transplantation (HSCT)." (PMID 34943994, 2021). "Individuals with the AG-CC genotype were found to have low levels of HPSE expression in normal neutrophils and LPS-activated MNCs, and a low risk of developing acute GVHD." (PMID 34685503, 2021). "Heterozygous AG individuals for rs4693608, which possessed the rs4364254 CC genotype, exhibited low heparanase expression and a low risk of developing acute GVHD." (PMID 34685503, 2021). "The enhancer SNP rs4693608 exhibited a leading function in the expression of the HPSE gene in normal neutrophils and LPS-activated MNCs, as well as in predicting the risk of acute GVHD post-transplantation." (PMID 34685503, 2021). "Our previous studies have shown that among several functional HPSE SNPs, the enhancer rs4693608 SNP has a major effect on the risk of acute GVHD post-HSCT." (PMID 34943994, 2021). "The C alleles of insulator SNPs rs4364254 and rs4426765 modify the activity of the HPSE enhancer, resulting in altered HPSE expression and increased risk of acute GVHD." (PMID 34685503, 2021). "Discrepancy in heparanase gene SNPs combinations between recipients and donors was found to be a risk factor for developing acute GVHD." (PMID 20419162, 2010). "We allocated all possible HPSE genotype combinations into three groups (HR, MR, and LR) correlating with high, intermediate and low heparanase mRNA expression levels and with high, intermediate and low risk of acute GVHD, respectively." (PMID 36980254, 2023). "This approach allowed distribution of all possible HPSE genotype combinations into three groups (HR, MR, and LR) correlating with high, intermediate, and low heparanase mRNA expression levels and high, intermediate and low risk of acute GVHD, respectively." (PMID 34685503, 2021). "In the present study, we assessed whether components of the patient’s and donor’s CMV serostatus may affect heparanase SNP-associated risk of acute GVHD after HSCT." (PMID 34943994, 2021). "We previously reported that disparities between recipient and donor pairs in SNP combinations of the HPSE gene significantly increase the likelihood of developing acute GVHD post-HSCT." (PMID 34685503, 2021). "Next, a univariate analysis of the cumulative incidence of clinically significant acute GVHD in correlation with the HPSE gene SNPs was performed separately in CMV-seropositive and CMV-seronegative groups." (PMID 34943994, 2021). "Moreover, the discrepancy between recipient and donor in HPSE SNPs contributes to the development of acute GVHD." (PMID 34943994, 2021).
Arthritis (4 papers, 2012 to 2025). Inflammation of a joint. "MMPs is known to play important roles for modulation of extracellular matrix structure and participate in pathological process such as cancer and arthritis; putting together, this study further implies an interplay of heparanase with MMP, which affects AA amyloid resolution." (PMID 22808071, 2012). "Through the positive feedback mechanism of heparanase, the synergistic upregulation of TFPI expression can restore hemostatic balance and enhance osteoblast activity, thereby improving bone tissue repair capability, which may facilitate arthritis repair." (PMID 40429617, 2025).
cholangiocarcinoma (4 papers, 2013 to 2021). A carcinoma that arises from the intrahepatic biliary tree (intrahepatic cholangiocarcinoma) or from the junction, or adjacent to the junction, of the right and left hepatic ducts (hilar cholangiocarcinoma). "The significant associations of EGFR, FLT1 and HPSE gene expression with survival warrant prospective evaluation of their usability in selecting more efficient treatment strategies for patients with cholangiocarcinoma." (PMID 23704979, 2013). "We determined the gene expressions of FLT1, FLT4, HPSE, Hif1a, HB-EGF, PDGFA, PDGF-RA and EGFR in FFPE samples of patients with cholangiocarcinoma." (PMID 23704979, 2013). "All three factors (expression of FLT1, HPSE and EGFR) were tested with ROC Analysis for their potential predictive capabilities in identifying patients with cholangiocarcinoma with a prolonged overall survival time (>3 years)." (PMID 23704979, 2013). "The HPSE expression was significantly increased in bladder urothelial carcinoma (BLCA), breast invasive carcinoma (BRCA), cholangiocarcinoma (CHOL), esophageal carcinoma (ESCA), lung adenocarcinoma (LUAD), lung squamous carcinoma (LUSC), stomach adenocarcinoma (STAD), and thyroid carcinoma (THCA)." (PMID 34461608, 2021).
dengue (4 papers, 2018 to 2023). "Taken together, our findings suggest that the increase of heparanase activity in dengue patients is associated with endothelial glycocalyx degradation and plasma leakage." (PMID 34987504, 2021). "It is yet to be elucidated whether heparanase activity plays a major role in dengue-associated plasma leakage." (PMID 34987504, 2021). "In summary, our study shows that plasma HPSE activity as well as the endothelial glycocalyx degradation products, HS and syndecan-1, are increased in acute dengue patients." (PMID 34987504, 2021). "Plasma HPSE activity levels in dengue patients at enrollment (n=30) were significantly increased compared to their values in the convalescence phase (n=25)." (PMID 34987504, 2021). "We provide further evidence for a role of HPSE-mediated degradation of the glycocalyx in acute dengue." (PMID 34987504, 2021). "Heparanase activity (plasma and urine), and heparan sulfate and syndecan-1 (plasma levels) were measured in dengue patients with thrombocytopenia in acute phase (n=30), during course of disease (n=10) and in convalescent phase (n=25)." (PMID 34987504, 2021). "In line with our current findings, several ex vivo and in vitro studies have previously explored the role of HPSE protein in dengue." (PMID 34987504, 2021). "Moreover, HPSE activity was associated with disease severity and several clinical markers of plasma leakage, thereby strengthening the possibility that HPSE may be key for initiating the vascular leakage observed in dengue." (PMID 34987504, 2021). "In summary, degradation of the endothelial glycocalyx is observed in acute dengue patients, which most likely is mediated by increased HPSE activity." (PMID 34987504, 2021). "HPSE activity was evaluated in plasma and urine of dengue patients and related to plasma leakage parameters and endothelial glycocalyx degradation products." (PMID 34987504, 2021). "Since a relatively high amount of heparanase is stored in platelets, we postulate that heparanase released by activated platelets contributes to the increased plasma heparanase activity during dengue virus infection." (PMID 34987504, 2021). "In line with these previous findings, our current data further provide proof by establishing relationships between increased plasma HPSE activity and endothelial glycocalyx degradation markers in acute dengue." (PMID 34987504, 2021). "In line with our current finding, a recent report showed that intra-platelet HPSE mRNA expression in dengue patients is increased." (PMID 34987504, 2021). "Cathepsins are also among the potent activators of heparan-degrading enzymes (e.g. heparanase and sialidase) and therefore may contribute to degradation of endothelial glycocalyx in dengue." (PMID 36595532, 2023). "Inhibition of HPSE might therefore prove a treatment option to prevent disruption of the endothelial glycocalyx barrier function in dengue." (PMID 34987504, 2021). "Therefore, our present data strengthen the notion that increased plasma HPSE activity is an important mediator of endothelial glycocalyx disruption and plasma leakage in patients with dengue virus infection." (PMID 34987504, 2021). "further demonstrated the presence of HPSE protein in the sera of dengue patients." (PMID 34987504, 2021). "To date, no studies have examined HPSE activity levels in dengue patients and the associations with glycocalyx disruption and plasma leakage." (PMID 34987504, 2021). "In this study we demonstrate the increase of plasma HPSE activity in hospitalized patients with acute dengue virus infection and further explore its relationships with markers of plasma leakage, endothelial glycocalyx degradation, albuminuria and bleeding manifestations." (PMID 34987504, 2021). "Heparanase activity was elevated in acute dengue and normalized during convalescence." (PMID 34987504, 2021). "Moreover, the major source of heparanase secretion and activation in dengue remains elusive." (PMID 34987504, 2021).
dengue (continued). "Altogether, our data suggest that thrombin and DENV2 virus, but not DENV NS1, might contribute to the increased plasma HPSE activity in acute dengue patients." (PMID 34987504, 2021).
endotoxemia (4 papers, 2020 to 2023). "In this study, the authors found that heparanase inhibition prevented endotoxemia-associated EG shedding." (PMID 32974033, 2020).
head and neck cancer (4 papers, 2012 to 2022). A primary or metastatic malignant neoplasm affecting the head and neck. "Heparanase is tightly implicated in head and neck cancer progression; yet, molecular mechanisms underlying transcriptional activation of the heparanase gene in HNSCC are largely unknown." (PMID 24286246, 2014). "This resemblance, taken together with the established role of both HPV and heparanase in HNSCC tumourigenesis, prompted us to examine the effect of HPV16 oncogenes on heparanase expression in head and neck cancer." (PMID 24286246, 2014).